COL18A1-AS1 (COL18A1 antisense RNA 1)
Synonyms: PRED80; C21orf123; NCRNA00175
Gene: Long non-coding RNA gene on chromosome 21 (45,419,716 to 45,425,070, reverse strand). Ensembl gene ENSG00000183535.
Diseases named in the same sentence as COL18A1-AS1 in open-access papers:
COL18A1-AS1 is named in the same sentence as 3 diseases in open-access papers, as found by Europe PMC text mining. Sharing a sentence is not in itself a finding about the gene and the disease.
COL18A1-AS1 shares sentences with these, for which no sentence is quoted: breast carcinoma (1 paper); non-small cell lung carcinoma (1); tumor (1).